PCGEM1 (PCGEM1 prostate-specific transcript)
Diseases named in the same sentence as PCGEM1 in open-access papers (continued):
Sharing a sentence is not in itself a finding about the gene and the disease.
tumor (31 papers, 2013 to 2025). "PCGEM1 also encodes an androgen-regulated lncRNA that is expressed exclusively in glandular epithelial cells of both normal and tumor specimens of human prostate." (PMID 23708091, 2013). "In patients, tumor-associated overexpression of PCGEM1 was detected in 84% of the samples." (PMID 23708091, 2013). "Additionally, tumor xenograft growth in a mouse model and clinical features in patients, such as tumor stage and metastasis, were found to be significantly associated with PCGEM1 dysregulation." (PMID 35265529, 2022). "They found that reducing PCGEM1 expression enhanced the inhibitory effect of baicalein on tumor cell proliferation and colony formation, induced apoptosis and autophagy and increased the sensitivity of LNCaP cells to baicalein." (PMID 37837401, 2023). "For example, the lncRNA prostate cancer gene expression marker 1 (PCGEM1) enhances tumor malignancy by regulating CDK6 expression." (PMID 36131071, 2023). "LncRNA PCGEM1 was initially discovered to be overexpressed in prostate cancer and to promote tumor growth." (PMID 37837401, 2023). "In recent years, accumulating studies have uncovered that PCGEM1 is abnormally expressed and functions as a powerful tumor regulator in NSCLC." (PMID 35265529, 2022). "The results showed that PCGEM1 levels in tumor tissues were approximately 4-fold higher than those in normal tissues." (PMID 35412947, 2022). "As an important member of the lncRNA family located on chromosome 2q32, PCGEM1 has been confirmed to function as a tumor promotor in diverse tumors." (PMID 35265529, 2022). "The close relationship between PCGEM1 and clinical features, including tumor stage, metastasis and overall survival rate, has also been well demonstrated." (PMID 35265529, 2022). "We found that the tumor volume and weight in nude mice which injected with PC-3 cells transfected with si-PCGEM1#1 were remarkably reduced, compared with si-NC in nude mice." (PMID 35109849, 2022). "In contrast to the sh-NC group, the tumor morphology and volume of nude mice in the low PCGEM1 expression group were smaller." (PMID 35412947, 2022). "For further verification the role of PCGEM1 in animal models, PC-3 cells transfected with si-NC and si-PCGEM1#1 were injected into mice subcutaneously, then the tumor volume and weight were measured." (PMID 35109849, 2022). "For example, PCGEM1 can upregulate anaerobic glycolysis, pentose phosphate pathway, lipid metabolism and glutamine metabolism to promote tumor cell proliferation." (PMID 30513511, 2018). "In particular, DIM reduces tumor growth by suppression of PCGEM1 and promoting apoptosis in the castrated xenograft mouse model." (PMID 27682980, 2016). "Of interest, suppression of PCGEM1 by DIM significantly reduced tumor growth and the tumor weight in castrated male mice." (PMID 27682980, 2016). "Together, these results suggest that DIM-related tumor growth suppression is associated with the downregulation of PCGEM1 and AR3 possibly through its interaction with PCGEM1 promoter." (PMID 27682980, 2016). "Transfection of the miR-145 expression vector and siRNA PCGEM1 inhibited tumor cell proliferation, migration, and invasion, and induced early apoptosis both in vitro." (PMID 25200485, 2014). "However, more research is needed to understand the relationship between PCGEM1, baicalein sensitivity or drug resistance and tumor cell autophagy, as well as the specific regulatory mechanism." (PMID 37837401, 2023). "Prostate Gene Expression Marker 1 (PCGEM1), a recently identified lncRNA, has been reported to play a crucial role in the initiation and progression of multiple tumors by interacting with pivotal regulators of tumor-related signaling pathways." (PMID 35265529, 2022). "The tumor was weighed, showing that PCGEM1 silencing attenuated the tumor weight." (PMID 35412947, 2022). "Thus, the clinical expression profile of PCGEM1 warrants further research in different tumor stages." (PMID 35265529, 2022).
tumor (continued). "An article published in Nature suggested that shRNA-mediated inhibition of PCGEM1 strongly suppressed tumor growth in a CWR22Rv1-induced PC xenograft mouse model, indicating a significant regulatory effect of PCGEM1 on the growth of castration-resistant prostate cancer (CRPC)." (PMID 35265529, 2022). "Furthermore, the expression level of PCGEM1 is significantly correlated with tumor-node-metastasis (TNM) stage and tumor differentiation in GC." (PMID 35265529, 2022). "Furthermore, siRNA PCGEM1 had a potent diminishing effect on PC tumor volume, whereas PCGEM1 overexpression had an adverse effect." (PMID 35265529, 2022). "Are there other tumor-related factors co-acting with PCGEM1?" (PMID 35265529, 2022). "Moreover, the overexpression of PCGEM1 is positively correlated with PC initiation, progression and chemotherapy resistance, which indicates the potential tumor-related functions of PCGEM1." (PMID 35265529, 2022). "PCGEM1 knockdown inhinited the tumor growth in vitro and in vivo." (PMID 35109849, 2022). "Moreover, animal xenograft experiment was performed and PCGEM1 knockdown delayed tumor growth in vivo." (PMID 33589577, 2021). "Herein, we first demonstrated a tumor-promotive function of lncRNA PCGEM1 in CC cells." (PMID 31832017, 2019). "Thus, PCGEM1 can provide growth advantages for PC cells by regulating tumor metabolism via c-Myc activation." (PMID 30037351, 2018). "Interestingly, the tumor suppressor miR-145 was found to bind prostate cancer gene expression marker 1 (PCGEM1), decreasing its expression, while downregulation of PCGEM1 increased miR-145 expression." (PMID 28783103, 2017). "Furthermore, suppression of PCGEM1 significantly reduced tumor growth and the tumor weight in castrated male mice." (PMID 26848868, 2016). "Similarly, PCGEM1 is specifically expressed in the prostate, and up-regulated in tumor tissue of prostatic origin compared with matched normal prostate tissue samples." (PMID 26516918, 2015). "Moreover, miR-145-mediated suppression of PCGEM1 suppressed tumor growth in vivo and PCa cell proliferation and invasive capacity in vitro." (PMID 25200485, 2014). "Finally, we investigated whether miR-642a-5p inhibitor could antagonize the anti-tumor effects of sh-PCGEM1." (PMID 38948025, 2024). "Similarly, the PCGEM1 expression level in EC was positively correlated with the tumor stage." (PMID 35265529, 2022). "LncRNAs, such as HOTAIR, PCGEM1, H19, and UCA1, are dysregulated in many types of tumor tissues and can function either as oncogenes or tumor suppressors through regulating cancer cell growth, apoptosis, and invasion." (PMID 38195623, 2024). "Downregulation of PCGEM1 or CDT1 inhibited the viability, promoted apoptosis and cycle arrest of PCa cells in vitro, and controlled tumor growth in vivo." (PMID 35412947, 2022). "PCGEM1-shRNA, through lentiviral packaging and injection into castrated male SCID mice, restrains tumor growth, suggesting that PCGEM1 can act as a likely drug target of castration resistance." (PMID 33407694, 2021). "Similar to PRNCR1 and PCGEM1, yet through a different mechanism, CTBP1-AS enhances AR transcriptional activity and promotes both hormone-dependent and castration-resistant tumor growth by repressing the AR-corepressor, CTBP1." (PMID 26690121, 2015). "Tumor suppressive lncRNAs (GAS5, MEG3, FER1L4 and LINC00672) and oncogenic lncRNAs (CCAT2, BANCR, NEAT1, MALAT1, H19, Linc-RoR, TUG1, TDRG1 and PCGEM1) may be a few such examples." (PMID 30781521, 2019). "We demonstrate a reciprocal negative control relationship between PCGEM1 and miR-145 that regulates both LNCaP cell proliferation and nu/nu PCa tumor growth." (PMID 25200485, 2014).
tumor (continued). "On the one hand, we did not study the effect of PCGEM1 on tumor metastasis in vivo." (PMID 35412947, 2022). "Thus, it is obvious to find a reciprocal negative control relationship between PCGEM1 and miR-145 that regulates both LNCaP cell proliferation and PC tumor growth." (PMID 30037351, 2018).
PCGEM1 also shares sentences with these, for which no sentence is quoted: breast carcinoma (3 papers); laryngeal carcinoma (1); liver cancer (1); lymphoma (1); metastasis (1); oral carcinoma (1); oral squamous cell carcinomas (1); pancreatic cancer (1); prostate (1); renal cell carcinoma (1); squamous cell carcinoma (1); testicular cancer (1).